ABCB1 (ATP binding cassette subfamily B member 1)
Diseases named in the same sentence as ABCB1 in open-access papers (continued):
Sharing a sentence is not in itself a finding about the gene and the disease.
tumor (continued). "ABCB1, ABCC1\2\3, ABCG2, ERCC1, XRCC1\2 can induce tumor chemo-resistance and radio-resistance." (PMID 37283789, 2023). "The structure of Lissodendrins B and the third-generation ABCB1 inhibitors OC144-093 have similar ‘Y’-type skeleton structural characteristics and may have ABCB1 inhibitory activity to reverse tumor MDR." (PMID 37233508, 2023). "Up regulation of ATP-binding cassette(ABC) transporter super family proteins such as ABCB1, ABCG2 and ABCC1 which pump chemotherapeutic drugs out of tumor cells thereby reducing intracellular drug accumulation have been observed as the most common mechanism of chemotherapy resistance." (PMID 37654838, 2022). "In addition, 33 survival-related genes were observed to be elevated in tumor tissues, whereas 4 genes (RBP4, ABCB1, SCNA, and MAPT) showed increased expression in normal tissues." (PMID 35873484, 2022). "Moreover, associations between the expression of several genes or proteins and the benefits of paclitaxel, such as CCND1, ABCB1, BCL-2, and SPARC in different tumor types, have been reported in multiple studies 25–29." (PMID 35595817, 2022). "The abundance of ABCB1 mRNA is increased in most CRCs, being significantly higher in well-differentiated than in poorly differentiated tumors regardless of tumor location and size." (PMID 35884584, 2022). "Consistently, Zn2+ stimulated ABCB1 expression and reduced DOX accumulation in tumour cells." (PMID 36207295, 2022). "Additionally, a positive correlation between ABCB1 methylation, the WHO tumor grade, and an IDH1 wild-type status has been observed." (PMID 36233525, 2022). "In contrast to CUDC-101, CUDC-907 was not a substrate of P-gp (ABCB1) transporters, and its antiproliferative activity was conserved in P-gp-expressing tumor cells." (PMID 35582529, 2022). "In both ABCB1-mediated MDR tumor xenograft models, no notable difference was observed in tumor growth among nude mice treated with normal saline, MRTX849 or paclitaxel alone." (PMID 36104708, 2022). "Western blotting analysis of tumor tissues afflicted with liver metastasis indicated that anlotinib could significantly inhibit EGFR and ABCB1 expression in vivo." (PMID 33754008, 2021). "Collectively, these data indicated that anlotinib could suppress tumor metastasis, angiogenesis, and multidrug resistance which reduced MET, EGFR, and ABCB1 expression in CRC liver metastasis and subcutaneously implanted xenograft model." (PMID 33754008, 2021). "Though there are indications in the literature that ABCB1 mRNA and protein are driven by Hippo/YAP signaling in both tumor cells and ovarian CSCs, further experimental evidence is required to ascertain direct or indirect as well as positive or negative transcriptional regulation." (PMID 35582031, 2021). "This protein, also known as ATP-binding cassette subfamily B member 1 (ABCB1) or ABC transporters, comprises a superfamily of efflux pump proteins with different members that may be involved in the MDR phenotype of tumor cells." (PMID 33923200, 2021). "Interestingly, several BBB-related transporters, including SLC2A1, ABCG2, ABCB1, SLCO1A2, and ATP10A were significantly decreased in ECs in tumor core." (PMID 34228647, 2021). "Besides, CSCs also express high levels of specific ABC drug transporters containing ABCB1, ABCG2, and ABCC1, which are known MDR genes in tumor cells, allowing for increased survival." (PMID 34950650, 2021). "It has shown downregulation of P-gp, BCRP, MRPs, and ABC transporter genes (ABCB1, ABCG2, and ABCC1), which may reverse MDR in tumor cells." (PMID 34680470, 2021). "For the castration-induced regression nadir group (i.e., those with the weakest or most unsuccessful castration-induced tumor regression), GSE1, CYP3A5, CTNNB1, CYP3A4, POU5F1, ABCB1, alkaline phosphatase liver/bone/kidney isozyme (ALPL), PROM1/CD133, ABCG2, and SOX2 were concomitantly upregulated." (PMID 34439112, 2021).
tumor (continued). "Of note, this inverse correlation of MARCKS and ABCB1 expression was also observed in three tumor samples with highly phosphorylated MARCKS (data not shown), suggesting that the phosphorylation status of MARCKS is relevant for its impact on ABCB1 function." (PMID 32056006, 2020). "While these classical “tumor cells” markers of gemcitabine sensitivity were not part of the GE signature, one of the genes ABCB1, an efflux pump of the (ABC) transporter family proteins was demonstrated to be involved in gemcitabine resistance." (PMID 33143297, 2020). "Two efflux transporters from the ATP-binding cassette (ABC) family, ABCB1 and ABCG2, may contribute to MDR by restricting the entry of therapeutic drugs into tumor cells." (PMID 31729540, 2020). "ABCB1 inhibitors reverse MDR by inhibiting ABCB1 transporter efflux activity or by down-regulating ABCB1 protein expression, reducing the efflux of chemotherapeutic drugs and therefore increasing drug accumulation in tumor cells." (PMID 32793491, 2020). "However, this uptake is opposed by action of ABC membrane transporters, such as ABCB1, MRP1 (ABCC1), and ABCG2, which excrete the radiotracer into extracellular space of tumor cells." (PMID 32562004, 2020). "Tumor uptake of [18F]AVT-011, measured as AUC of %ID/g*min from 5–42.5 min, was 15% lower in the intermediate group (Padj = 0.10) and 32% lower in the high ABCB1–expressing group (P < 0.001) than in the basal group." (PMID 31729540, 2020). "The ABCB1 but not the ABCG2 promoter methylation status was significantly higher in tumor tissues than in healthy brains serving as controls." (PMID 33066132, 2020). "We found increased ABCB1 expression in MARCKS negative CRC patient tumor samples and established CRC cell lines." (PMID 32056006, 2020). "For example, the covalent introduction of a phospholipid to generate porphyrin-lipid derivatives might deal with ABCB1-mediated BPD extrusion and alleviate PDT-resistance of tumor cells." (PMID 33552982, 2020). "In tumor tissues, the ABCB1 promoter was significantly higher methylated than in non-neoplastic mucosa." (PMID 33066132, 2020). "Recently, we found that gefitinib inhibits both ABCB1 and ABCG2, and that the antitumor activity, tumor tissue, and blood concentrations of SN-38 (the active metabolite of irinotecan) are increased in tumor-bearing mice by administration of gefitinib in combination with irinotecan." (PMID 31340525, 2019). "It is interesting to note that both etoposide and teniposide are also recognized by ABCG2, and etoposide is additionally recognized by ABCB1, which may mask the OATP2B1-mediated effect in tumor cells expressing several transporters." (PMID 30863990, 2019). "Tumour samples were scored as positive or negative for membranous ABCB1 expression using immunohistochemistry (tumours with only vascular staining were scored as negative)." (PMID 31311995, 2019). "Compared to ABCB1 negative patients with complete resection, ABCB1 positive patients are more likely to relapse, in particular those who had incomplete tumour resection (hazard ratio 2.64, 95% CI 1.22–5.73)." (PMID 31311995, 2019). "In addition, quantitative targeted absolute proteomics (QTAP) was applied to determine ABCB1 and ABCG2 levels in surgically resected tumor tissue." (PMID 31832814, 2019). "In addition, ABCB1 and ABCG2 levels were determined in surgically resected tumor tissue of four patients using quantitative targeted absolute proteomics." (PMID 31832814, 2019). "In that way, ABCB1 contributes to the acquisition of a multidrug resistant (MDR) phenotype since it can bind and extrude a huge repertoire of drugs, thus leading to treatment failure and tumor relapse." (PMID 31921125, 2019). "This phenomenon is known for many years in ABCB1 (P-gp/MDR1) and MRP1overexpressing tumor cells." (PMID 30349477, 2018).
tumor (continued). "In this study, we provide strong evidence that bile acids can selectively reduce doxorubicin accumulation into ABCC1-expressing (but not ABCB1-expressing) tumour cells." (PMID 29615646, 2018). "Although the role of efflux pump P-glycoprotein (Pgp), codified by the ABCB1 gene, is unquestionable in drug resistance of many neoplasms, a longstanding question exists about whether Pgp has a firm implication in TKI resistance in the clinical scenario." (PMID 29316665, 2018). "Many studies have reported that the three monomers of curcuminoids reverse the overexpression of ABC transporters including ABCB1, ABCG2, and ABCC1 in drug resistant tumor cells without causing systemic toxicity." (PMID 28591733, 2017). "Since ABCB1 and ABCG2 are the major drug-efflux transporters at the BBB, that are highly expressed in Group 3 MB and MYCN-amplified SHH-MB, it would be beneficial to determine if these transporters are expressed at the tumor ECs of the various MB subgroups." (PMID 29186899, 2017). "In tumor adjacent tissues, the promoter methylation status of ESR2 correlated with that of MGMT (r = 0.704, p = 0.002) and in tumor-distant tissues, the methylation status of APC correlated with that of ABCB1 (r = 0.756, p < 0.001)." (PMID 28403857, 2017). "We found that lack of ABCB1/MDR1-mediated signals promoted a B cell-dominated tumor immunogenic microenvironment and resulted in an increase in tumor cell damage, which correlated with inhibition of inflammation-associated tumor growth." (PMID 28686677, 2017). "In contrast, expression of ABCB1 mRNA was consistently decreased in tumor lesions of CRC, when compared to adjacent normal, non-inflamed colonic mucosa (R0)." (PMID 28686677, 2017). "Treatment of tumors with an ABCB1 inhibitor, verapamil, enhanced saridegib’s ability to reduce GLI1 level even after extended treatment periods, highlighting the role of ABCB1 in mediating tumor growth in this SHH-MB model." (PMID 29186899, 2017). "No ABCB1 protein expression was observed in 6 out of 12 colonic specimens of inflamed but tumor-free margins from CAC patients." (PMID 28686677, 2017). "We observed an intimate relationship of ABCB1 expression in recurrent tumor with OS, but not that in primary tumor." (PMID 27812204, 2016). "In addition to the basic characteristics, 6 and 4 studies assessed the impact of ABCB1 on OS and PFS, respectively, adjusted for age, clinical stage, residual disease, histological type and tumor grade by multivariate analysis." (PMID 27812204, 2016). "Each of the CpGs in the ABCB1 and ABCG2 promoters was methylated in ≥ 75% of the tumor tissues." (PMID 27689338, 2016). "Furthermore, tumour uptake of the most recent iteration of irreversible EGFR imaging agents, [18F]afatinib, was sensitive to modulation by the ABCB1-specific inhibitor, tariquidar." (PMID 27552105, 2016). "In a previous study, the translocations resulting in hybrid mRNA containing ABCB1 gene mRNA were observed with or without co-amplifications of these hybrid genes in some drug-resistant human tumor cell lines and in patients with refractory leukemia." (PMID 29061940, 2015). "Elevated expression of ABCB1, ABCG2, and ABCCs mRNA in pancreatic adenocarcinomas compared to normal pancreas has been reported, but correlation with clinical aggressiveness of the tumor remains controversial." (PMID 24883056, 2014). "SL exposure also induced changes in the expression of genes involved in metabolic functions in tumor and stem cells (ALDH1B1, ABCB1, SLC3A2, SLC44A2, SLC31A2, SLC7A11, CYP24A1, PTGS2/COX2, PPRC1), cytokines (CCL3L3, GDF15) and growth and differentiation factors (PGF, TGFBR11 and FOXD1)." (PMID 24742967, 2014). "Only three tumor biopsies showed increased ABCB1 expression without concurrent increases in Wnt5A after chemotherapy." (PMID 25401518, 2014).
tumor (continued). "Interestingly, the increased ABCB-1 mRNA and P-gp protein levels in the EPI group’s tumor tissue were confirmed by real-time PCR and Western blotting." (PMID 25372840, 2014). "Immunostaining confirmed the presence of ABCB1 in PDAC, mainly located at the apical surface of the tumor cells where active drug transport may occur." (PMID 24069258, 2013). "All four of those tumor lines, HCT116, Colo201, Colo205, and RKO show low ABCB1 gene expression." (PMID 23524533, 2013). "We, therefore, assume that pharmacokinetics of olomoucine II will be affected by both ABCB1 and ABCG2 transport proteins, which might potentially result in limited accumulation of the compound in tumor tissues or lead to drug-drug interactions." (PMID 24116053, 2013). "Although low-signal ABCB1 immunoreactivity was also observed in a few endothelial cells and some (tumor-infiltrating) lymphocytes, the tumoral stroma mostly lacked ABCB1 expression." (PMID 24098529, 2013). "Given the hypoxic nature of tumor cells, whether histone deacetylation is involved in the inhibition of ABCB1 expression in the BRL hypoxia model has not been confirmed." (PMID 40265153, 2025). "Among our ACC cell-line derived xenografts, CU-ACC1 had lower surface ABCB1 expression than H295R, which could at least partially explain the long-term tumor control with ADCT-701 treatment in CU-ACC1 but not H295R tumors." (PMID 40595495, 2025). "Our study discerned that miR‐21‐related genes, such as ABCB1, SPRY1, ERGE, PIK3R1, SPTBN1, VIM, and others, which experienced downregulation in tumor sites, exhibited a negative correlation with tumor purity and a positive association with T cell infiltration, notably CD8+ T cells." (PMID 40567015, 2025). "Furthermore, it has been shown that the expression of the ABCB1 and ABCG2 transporters at the endothelial cell luminal membrane in the BTB might be increased compared to the unaffected BBB and in tumor cells themselves." (PMID 40893689, 2025). "Among our ACC xenografts, CU-ACC1 had lower surface ABCB1 expression than H295R, which could at least partially explain the long-term tumor control with ADCT-701 treatment in CU-ACC1 but not H295R tumors." (PMID 39416174, 2024). "Of note, the presence of drug transporters (e.g., P-glycoprotein (ABCB1), breast cancer resistance protein BCRP (ABCG2), multidrug resistance protein 2 (MRP2) (ABCC2), multidrug and toxin extrusion protein 1 (MATE1) (SLC47A1)) at the BTB also influences the delivery of nanoparticles to the tumor." (PMID 37049234, 2023). "Moreover, sanguinarine and other BZD inhibited the P-glycoprotein/ABCB1 and related ABCB5 in drug resistance in multidrug-resistant tumor lines, increasing their sensitivity to cytotoxic drugs, which might allow for better treatments." (PMID 35209167, 2022). "However, it has also been documented that SFN does not induce changes in ABCB1 expression in different tumor lines." (PMID 36142752, 2022). "Another importance is that gene silencing of ezrin, but not of radixin and moesin significantly decreased the cell surface expression of P-gp without affecting the levels of the ABCB1 mRNA in LS180 cells cultured at the acidic pH condition which mimics the actual tumor microenvironment." (PMID 33974673, 2021). "Perhaps we could have identified fusions involving ABCB1 had we analyzed tumor samples obtained at the time of recurrence, rather than primarily evaluating the original tumor." (PMID 33946483, 2021). "Interestingly, our genomic analysis revealed that not all cells within the tumor population harbored ABCB1 fusions, raising the question of how fusion-negative cells have survived under chemotherapy-induced selective pressure." (PMID 34830797, 2021).
tumor (continued). "The expression of STAT5a, p-STAT5a and ABCB1 detected by IHC was significantly decreased in tumor tissues from the pimozide group and combination group but did not vary between the DOX group and PBS group, suggesting the potent effect of pimozide on suppressing STAT5a and downstream ABCB1." (PMID 34336684, 2021). "In this context, tumours with highly upregulated ABCB1 expression may be unlikely to respond to either THZ1 or ICEC0942, whereas tumours with high ABCG2 expression may derive benefit from ICEC0942 treatment." (PMID 31530935, 2020). "Moreover, ABCB1 and ABCC2 could play an overlapping function in elimination of hepatotoxicity of antitumor drugs, and in drug resistance of tumor cells to CP." (PMID 33240085, 2020). "By contrast, the increase in tumor uptake between 45 and 90 min in animals not treated with tariquidar was 10.4 ± 10.6% in the basal group (n = 4 mice) and 5.4 ± 12.6% in the high ABCB1–expressing group (n = 5 mice)." (PMID 31729540, 2020). "Specifically, for instance, “third generation” ABCB1 modulators, such as elacridar (GF120918), laniquidar (R101933), zosuquidar (LY335979), and tariquidar (XR9576) with only nanomolar concentrations of the inhibitors required to inhibit ABCB1-mediated pumping of drugs out of tumor cells effectively." (PMID 31681564, 2019). "Patient 9’s tumour sample very strongly expressed ABCB1 but without a detectable fusion." (PMID 30894541, 2019). "However, it is clear that for the differentiated tumours we examined in this study, the apical‐out expression of brush border proteins, such as ABCB1, does not reflect their in vivo polarity." (PMID 30306567, 2019). "Firstly, there is the possibility that radiotherapy, with its associated increased risk of secondary tumours and effects on the developing brain at all ages of childhood, could be avoided in ABCB1 negative tumours." (PMID 31311995, 2019). "ABCB1 mRNA expression levels were highly variable in UC-related colonic specimens, regardless of the histological diagnosis (active inflammation with or without tumor disease)." (PMID 28686677, 2017). "In contrast, ABCB1 mRNA levels were highly variable in CAC tumor and matched non-tumor tissues." (PMID 28686677, 2017). "Likewise, ABCG2 and ABCB1 expression levels in the original tumours did not explain the multidrug resistance observed in the derived cultures." (PMID 28877221, 2017). "However, there has been no study on the amplification of the ABCB1 gene in canine tumor cells with drug resistance." (PMID 29061940, 2015). "In the clinical trial of high doses of lapatinib conducted by Moasser and colleagues, it may be that the responses seen with lapatinib and ketoconazole were due to the ability of ketoconazole to inhibit ABCB1 in tumor, and not just CYP3A4 in the intestine." (PMID 26571496, 2015). "In these models we found that similar and reasonable average growth inhibition (42, 42, and 45%) was obtained, although the end of study tumor volumes between treated groups and controls were not statistically significant, but two of the three models had high ABCB1 gene expression and one did not." (PMID 23524533, 2013). "As far as we know, the ABC transporter-subfamily B member 1 (ABCB1/MDR1/P-glycoprotein, P-gp), subfamily C member-1/2 (ABCC-1/2, MRP-1/2), subfamily G member 2 (ABCG2, BCRP), and lung resistance-related protein (LRP) play a major role in producing MDR in tumor cells." (PMID 23533531, 2013).